IL13 (interleukin 13)
Diseases named in the same sentence as IL13 in open-access papers (continued):
Sharing a sentence is not in itself a finding about the gene and the disease.
asthma (continued). "This pathway is essential in the development of allergic asthma and is likely genetically controlled, evidenced by a polymorphism in the IL-4, IL-13, and RAD50 genes associated with asthma and atopy." (PMID 37265457, 2023). "Through the case–control study, the distribution differences of the genotype frequencies and allele frequencies in the four SNP loci: ADRB2 rs1042713, IL4 rs2243250, FCER1B rs569108, IL13 rs20541in asthma group and control group." (PMID 38049812, 2023). "We assessed the anti-inflammation and anti-allergic effect of stigmasterol in OVA-induced asthma mice and IL-13-induced BEAS-2B cells, and investigated if NK1R is the underlying target of stigmasterol in the treatment of asthma." (PMID 36788676, 2023). "The potential advantages of stigmasterol in asthma were explored in IL-13-induced BEAS-2B cells and asthmatic mice." (PMID 36788676, 2023). "T2 high asthma is primarily driven by cytokines (IL-4, IL-5, IL-13), eosinophil alarmins (IL-25, IL-33, thymic stromal lymphopoietin [TSLP]), and Immunoglobulin E (IgE)." (PMID 37189529, 2023). "Another cytokine that contributes to the pathophysiology of asthma is IL-13, a pleiotropic Th2 cytokine that contributes to goblet cell differentiation, activation of fibroblasts, and increased airway hyperresponsiveness." (PMID 37063828, 2023). "IL-4 and IL-13 play a powerful and intricate role in the type 2 cytokine response due to their effect on nearly every cell relevant to asthma." (PMID 37265457, 2023). "T helper 2 cells (Th2), as a primary source of the type 2 cytokines IL-4, IL-5, and IL-13, capable of driving all these immunological and physiological features, have therefore long been considered central to asthma pathogenesis." (PMID 37163370, 2023). "The increased expression of MUC5AC in TH2 asthma was likely induced directly by the TH2 cytokine IL-13, which has been shown to increase MUC5AC in both human airway epithelial cells and mouse models." (PMID 37443808, 2023). "Most patients with asthma have T2 inflammation, characterized by cytokines (IL-4, IL-5, and IL-13) and inflammatory cells (eosinophils, mast cells, basophils, and IgE-producing plasma cells)." (PMID 38203353, 2023). "Tralokinumab and Lebrokizumab are anti-human IL-13 monoclonal antibodies developed for the treatment of severe, uncontrolled asthma." (PMID 37259416, 2023). "Comparative analysis of allele and genotype frequenciesbetween the cohort of asthma patients and controls revealedstatistically significant differences in the SNPs distribution inthe promoter regions of IL4 rs2243250 and IL13 rs1800925." (PMID 37465198, 2023). "Dupilumab, another drug directed on T2 inflammation mechanisms, was precisely directed to the IL-4 receptor, which is a molecule that can interact both with IL-4 and IL-13 (currently used in atopic dermatitis, nasal polyposis, and asthma)." (PMID 37765327, 2023). "Kutlina T.G., Valova Ya.V., Karimov D.D., Kudoyarov E.R., MukhammadiyevaG.F., Karimov D.O., Kabirova E.F. The role of rs1800925gene IL-13 in the formation of broncial asthma in residents of theRepublic Bashkortostan." (PMID 37465198, 2023). "The disrupted and leaky barrier in asthma is well-documented and a positive feedback loop of IL-4 and IL-13 contributes to this phenotype seen in patients with asthma." (PMID 37520564, 2023). "Anti-IL13 drugs such as tralokinumab and lebrikimuzab have been investigated as potential add-on treatments in severe asthma." (PMID 36829959, 2023). "“Type-2-high” asthma is characterized by high secretion of interleukin (IL)-4, IL-5, and IL-13, elevated eosinophil counts, serum periostin, and total IgE, including allergic and eosinophilic asthma." (PMID 37377958, 2023). "Pendrin, as an anion transporter located at the apical side of airway epithelial cells, acts as a downstream effector of the IL-4/IL-13 signaling pathway and participates, e.g., in airway inflammation in asthma." (PMID 36768179, 2023).
asthma (continued). "Interleukin-13 (IL-13), a central regulator of Th2-dominated respiratory disorders such as asthma, abolished the increase in Aqp5 mRNA level during airway epithelial cell differentiation." (PMID 36768212, 2023). "It is believed that IL-5 and IL-13 play important roles in the etiology of asthma, with IL-13 acting on a different pathway from IL-5 to cause airway hyperreactivity (AHR) in the allergic lung." (PMID 37239461, 2023). "The central drivers of T2-high asthma are IL-4, IL-5, and IL-13 that drive airway inflammation through increasing eosinophils, basophils, and mast cells in the airways." (PMID 38259298, 2023). "The relevance of IL-4 and IL-13 in the pathophysiology of asthma has been extensively addressed throughout various studies and reports." (PMID 37199256, 2023). "In general, data coming from anti-IL13 RCTs in severe asthma substantially confirmed the observations reported with dupilumab." (PMID 36829959, 2023). "The levels of IL-4 and IL-13 were also found to be higher in children with recurrent wheezing, with the highest levels observed in those with asthma." (PMID 37760982, 2023). "This suggests that activated IL-5 and IL-4/IL-13 pathways can simultaneously contribute to airway inflammation in some cases of severe asthma." (PMID 37298514, 2023). "What is more, both TSLP and IL-13 are co-expressed in the lung epithelial tissues of severe asthma patients." (PMID 37334374, 2023). "Gene set enrichment analysis (GSEA) showed enrichment in asthma pathways, including increased IL-13, IL-4, and IL-5 expression." (PMID 37699899, 2023). "Derangements of Th cells are deeply involved in the pathogenesis of asthma, in which Th2-secreted cytokines such as IL-4, IL-5 and IL-13 promote the accumulation of eosinophils and Th17-produced IL-17 mediate neutrophil recruitment." (PMID 37449208, 2023). "Single cell RNA sequencing (scRNA-seq) analysis shows that ACE2 mRNA levels are decreased in the IL-13-stimulated tracheal airway basal epithelial cells and intermediate secretory cells of asthma patients." (PMID 37608279, 2023). "Airway hyperresponsiveness (AHR) exacerbation, immune cell influx, and mucus secretion in asthma are all controlled by IL-13." (PMID 37569348, 2023). "TSLP and IL-13 are attractive targets for asthma therapeutics due to their importance in asthmatic cellular signalling and overlap of the signalling effects of both cytokines." (PMID 37334374, 2023). "While ICS inhibits IL-13, a high proportion of uncontrolled asthma patients have elevated levels of IL-13 in their sputum despite treatment with high dosage ICS." (PMID 38259298, 2023). "Periostin is an extracellular matrix protein with an upregulated expression in airway epithelial cells and fibroblasts after activation by IL-13 and alarmin IL-33 in patients with some types of asthma and allergic inflammation, but also in pulmonary fibrosis." (PMID 40980110, 2023). "From a pathophysiological view, both disorders, CRSwNP, and asthma share the same type 2 immunopathology (involvement of IgE, eosinophils, interleukin-4 (IL-4)/IL-13, and IL-5) and exhibit epithelial barrier dysfunction." (PMID 37464395, 2023). "The anti-IL-4/IL-13 agent dupilumab is indicated for the treatment of both severe asthma and CRSwNP." (PMID 37088840, 2023). "Its blockade with neutralizing antibodies reduced inflammation and levels of IL-4, IL-5, and IL-13 cytokines in a murine ovalbumin-induced asthma model." (PMID 37762787, 2023). "Another therapeutic agent targeting both IL-4 and IL-13, pitrakinra, a dual IL-4/IL-13 antagonist, reduced asthma exacerbations only in a subgroup of patients with specific gene polymorphisms of IL-4 receptor." (PMID 37199256, 2023). "Th2 cells and the cytokines they secrete (IL-4, IL-5, IL-13, and IL-9) are responsible for most of the pathological changes seen in asthma." (PMID 37174726, 2023).
asthma (continued). "Among them, IL-13 has been shown to play a central role in asthma, mediating many of its key physiologic and pathological features." (PMID 36089628, 2023). "Dupilumab is a monoclonal antibody that targets interleukin (IL)-4 and IL-13 for use in moderate to severe eczema, asthma, and nasal polyposis." (PMID 37426396, 2023). "Th2 cytokines, including interleukin (IL)-5, IL-4, and IL-13 play a significant role in initiating the inflammatory cascade in asthma." (PMID 37063828, 2023). "Molecular pathophysiology of T2 asthma is fuelled by activated GATA-3+ CRTH2+ ILC2s as well as Th2 cells that produce substantial amounts of the hallmark type 2 cytokines: IL-4, IL-5, and IL-13." (PMID 37199256, 2023). "In asthma, an increase in C3 leads to innate lymphoid cell chemotaxis (ILC2), which ultimately raises the production of IL-4 and IL-13 and causes inflammation." (PMID 37422662, 2023). "Another review demonstrated that abnormal expression of miRNAs (miR-146a and miR-106b) was related to the production of Th2 cytokines (IL-5 and IL-13), which are both involved in the pathogenesis of asthma in children." (PMID 37629446, 2023). "GLP-1 agonists were also found to decrease eosinophilic-mediated secretion of IL4, IL8, and IL13 in mice with asthma." (PMID 36457601, 2022). "Further analysis on IL-5, IL-13, and IFN-γ levels showed that compared with the normal control, the asthma group had higher IL-5, IL-13 and TNF-α levels and lower IFN-γ levels." (PMID 35210449, 2022). "IL-4 and IL-13 can enhance bronchial remodeling and recruitment of mast cells, basophils, and eosinophils, aggravating airway inflammation in asthma." (PMID 36330226, 2022). "In certain severe asthma conditions, biologics such as omalizumab (anti‐IgE), mepolizumab, reslizumab and benralizumab (anti‐IL‐5 pathways), and dupilumab (anti‐IL‐4/IL‐13) represent major advances in asthma care." (PMID 40496383, 2022). "Other potential candidates for both AD and asthma are the anti-IL-13 mabs, tralokinumab and lebrikizumab." (PMID 35743678, 2022). "On the basis of the previous arguments, the present narrative review will be focused on two main topics: (i) pathophysiologic functions of IL-4 and IL-13 in type 2 asthma; and (ii) the role of dupilumab as an add-on biological therapy of severe asthma." (PMID 35746582, 2022). "IL-13 is a central effector cytokine in asthma and the pivotal regulator in IgE synthesis, goblet cell hyperplasia, airway remodeling, mucus hypersecretion, and airway hyperresponsiveness." (PMID 36326393, 2022). "The anti-interleukin-4 receptor α monoclonal antibody (Dupilumab) that blocks both interleukin-4 and interleukin-13 signaling significantly decreased the rates of severe asthma exacerbation, as well as improved lung function and better asthma control." (PMID 35672815, 2022). "These analyses revealed that critical processes for viral entry, replication, and spread, pertinent to asthma and COVID-19 severity, were affected by IL-13 treatment." (PMID 35353667, 2022). "IL-4 and IL-13 are main signature cytokines in type 2 immune response and are responsible for asthma and many other allergic inflammatory diseases." (PMID 35281601, 2022). "Research on asthma patients and mice models of the disease has shown that activation of Th2 and production of Th2 type cytokines such as IL-13, IL-4, and IL-5, lead to activation of eosinophils and production of IgE." (PMID 36249456, 2022). "Previous research by other members of the research team found that QF alleviated asthma exacerbation by decreasing the levels of IL-4, IL-6, and IL-13 in the serum and inflammatory cells in the lung tissue of RSV-infected asthmatic mice." (PMID 36081945, 2022). "Administration of anti-IL-6 antibodies during asthma induction increased IL-13, IL-4, and IL-5 protein levels in the BALF." (PMID 35408882, 2022).
asthma (continued). "As mentioned, this adjuvant induced higher levels of IL-13, a pleiotropic type 2 cytokine that has been shown to be integral in the pathogenesis of asthma and other eosinophilic disorders." (PMID 35844531, 2022). "Consistent with findings in animal models, it has been clinically proven that asthma patients showed elevated levels of IL-13 in the blood and sputum." (PMID 35697721, 2022). "These cytokines associated with the Th2 response induce IgE immunoglobulin production by B lymphocytes (IL-4), chemotaxis for eosinophils towards the lung microenvironment (IL-5), mucus and collagen secretion, and bronchial hyperreactivity (IL-13)." (PMID 36685604, 2022). "To confirm that IL-13 in our hands induces the main features of asthma in mice, we determined the airway resistance in response to escalating nebulized doses of methacholine." (PMID 35997279, 2022). "An asthma cell model was established with interleukins (IL-4, IL-13 and IL-17A) and transfected with siRNA-CXCR1." (PMID 36575422, 2022). "Patients with this profile are the most common participants included in the asthma studies for novel T2‐inflammation focused therapeutics, for example, anti‐IL‐13 and anti‐IL‐5 monoclonal antibodies." (PMID 35305052, 2022). "STAT6 is activated by cytokines IL-4 and IL-13 and mediates the occurrence of allergic diseases, such as asthma, atopic dermatitis, and eosinophilic esophagitis." (PMID 35204186, 2022). "Many studies have shown that type 2 cytokines, including interleukin (IL)-4, IL-5, and IL-13, were related to allergic inflammation and these cytokines elevated in the sputum and the blood of patients with asthma and AR." (PMID 35348596, 2022). "IL-13 or IL-33 stimulation of 16 human bronchial epithelial (16HBE) cells was conducted to simulate the cell environment of T2 asthma." (PMID 35480331, 2022). "They found IL-5 and IL-13 producing CD34+ stem cells were present in the sputum of patients with asthma, and increased after allergen challenge." (PMID 36177009, 2022). "Aberrant T helper type 2 (Th2) inflammation is the most important pathological process for asthma, which is mediated by Th2 cytokines, such as interleukin (IL)-5, IL-4, and IL-13." (PMID 36078171, 2022). "Type 2 innate lymphoid cells (ILC2s) are also important mediators of asthma by producing IL-5, IL-13 and cross­regulating conventional T cells." (PMID 36524132, 2022). "Pediatric asthma is mainly characterized by a T helper type (Th)-2-inflammation in which the release of interleukin (IL)-4, IL-13, IL-5, and the immunoglobulin E (IgE) production increase eosinophilic survival." (PMID 36483465, 2022). "The concentration of IL-4 and IL-13 was significantly increased in the blood of pediatric asthma patients relative to the healthy control group." (PMID 36313877, 2022). "Both hydroprednisone therapy and glucocorticoid-induced transcript 1 (GLCCI1) overexpression repressed the airway remodeling in asthma mice model via suppressing IL-13/periostin/TGF-β1 axis." (PMID 36611844, 2022). "Many mechanisms can sustain corticosteroid resistance in asthma, including an exaggerated production of IL-5 and IL-13, an excessive expression of the dysfunctional GRb isoform, and an impairment of histone deacetylases." (PMID 36140282, 2022). "TSLP, IL-33 and IL-25 are epithelial cell-derived cytokines that stimulate group 2 innate lymphoid cells (ILC2s) to release type 2 cytokines such as IL-5 and IL-13 and play an important role in asthma pathogenesis." (PMID 35292112, 2022). "Th2-asthma (i.e., eosinophilic asthma) is well established to play a leading role in asthma development as more than half of asthma cases have a Th2 phenotype, characterized by the secretion of high levels of IL-4, IL-5, and IL-13 by Th2 cells." (PMID 35769905, 2022). "IL-4 and IL-13 contribute to asthma pathogenesis also by impairing the integrity of the airway epithelium." (PMID 35625801, 2022).
asthma (continued). "Higher IL-13 levels have been detected in BALF and lung tissue of patients with asthma, and previous studies have confirmed that excessive IL-13 secretion from Th2 cells deteriorates respiratory function." (PMID 35682783, 2022). "Over the past few years, compelling evidence of IL-13 as a key mediator and critical effector molecule in the inflammatory processes of asthma and COPD has been established." (PMID 35677382, 2022). "In support of this, type 2–high asthma is characterized by elevated levels of IgE and Th2 cytokines, including IL-4, IL-5, and IL-13." (PMID 34536215, 2022). "The transition of increased Muc5ac transcription in mucus-secreting cells was similar to the IL13-induced metaplastic process in human asthma airway epithelial cells." (PMID 35869072, 2022). "IL-13 has been increasingly recognized for its role in inflammatory conditions, such as asthma, ulcerative colitis and eosinophilic oesophagitis but also in diseases with a strong fibrosis component." (PMID 35194091, 2022). "In asthma pathogenesis, Th2 cells produce various cytokines, including interleukin (IL)‐5, IL‐9, and IL‐13, orchestrating immune responses." (PMID 35344296, 2022). "Th2 cells secrete IL-4, IL-5, IL-9, IL-13 and other inflammatory factors, among which IL-4 and IL-13 are the regulators of asthma." (PMID 35744915, 2022). "Intranasal administration of let-7 mimics reduced IL-13 levels in allergic lungs and alleviated asthma features, such as airway hyper responsiveness, airway inflammation, and goblet cell metaplasia." (PMID 36313425, 2022). "Then, in the experiment of PEF against asthma, our findings showed that the expression of IgE, IL-4, IL-5, IL-6, IL-13, and IL-17 were significantly higher in the model group." (PMID 36172200, 2022). "In a 52-week RCT of tralokinumab, another anti-IL13 mAb, significant improvements in asthma exacerbation rate, lung function, and asthma symptoms were also found in patients with increased pre-treatment periostin serum levels." (PMID 36226150, 2022). "CLCA1 is highly expressed in children with asthma and mediates the contributory effect of IL-13 on the occurrence and development of pediatric asthma." (PMID 36313877, 2022). "Secondly, patients with asthma have increased levels of plasma cytokines such as IL-4, IL-5, and IL-13 and chemokines such as monocyte chemoattractant protein-1 (MCP-1)." (PMID 35905078, 2022). "The hub gene ITLN1, which is expressed in airway epithelial cells and involved in inflammatory pathways downstream of IL-13, was found to be significantly upregulated in the bronchial brushings of patients with asthma compared with controls." (PMID 35550122, 2022). "PBMCs from asymptomatic infants that developed asthma by age 7 secrete higher levels of T2 cytokines (IL-5 and IL-13) and IL-17 when exposed to Mcat or NTHi, and Mcat promotes IL-8 and IL-33 gene upregulation in A549 human alveolar epithelial cells." (PMID 35386652, 2022). "In all these settings, a pro-inflammatory state is ultimately promoted by the immune system, in which T-helper type 2 (Th2) cells express interleukin (IL)-4 and IL-13, and have been described as promoters of acute inflammation in the pathogenesis of asthma." (PMID 36613991, 2022). "Such structural changes express the powerful action of IL-13 as a central mediator of airway remodeling in asthma." (PMID 35350765, 2022). "These patients require disease-modifying therapeutic agents such as targeted agents against IL-4/IL-13 that can shift the natural course of disease progression in AR and asthma." (PMID 35663523, 2022). "The release of IL-25 from epithelial cells in asthma also leads to overproduction of IL-4, IL-5, IL-9, IL-13, and CCL11, which then initiate recruitment of eosinophils, DCs, ILC2s, basophils, T cells, and other immune cells." (PMID 36311787, 2022).